CCND1 (cyclin D1)
Diseases named in the same sentence as CCND1 in open-access papers (continued):
Sharing a sentence is not in itself a finding about the gene and the disease.
cancer (continued). "The identification of mutations within SCFFbx4-αBcrystallin ligase in primary tumors provides mechanistic insight into cyclin D1 accumulation in human cancer." (PMID 18764945, 2008). "This is consistent with the known increase of CCND1 in many cancers and the observed decrease of CCND1 in multiple cancer cell lines." (PMID 19784388, 2008). "Carcinomas with 11q13 amplification showed high protein expression levels in 8/8 cases for cyclin D1, 8/9 cases for FADD and 8/9 for cortactin." (PMID 18268491, 2008). "Deregulated cyclin D1 degradation appears to be responsible for the increased levels of cyclin D1 in several cancers." (PMID 17407548, 2007). "Combined, these data support the contention that cyclin D1 is differentially localised in cancer, and that cytoplasmic cyclin D1 can correlate with proliferative outcomes in a tissue specific manner." (PMID 17375037, 2007). "Several conventional and experimental anti-cancer agents have been observed to induce cyclin D1 degradation in a wide range of cancer cell lines." (PMID 17407548, 2007). "The importance of cyclin D1 in cancer makes it an attractive target for anti-cancer therapy and ablative agents are currently in development." (PMID 17407548, 2007). "In some systems, cancer cell lines are dependent on a cyclin D1 oncogene for survival (oncogene addiction)." (PMID 17683622, 2007). "The siRNA mediated knockdown of CUL1, CUL7 and FBXW8 in HCT116, SW480, U-2 OS and T98 cancer cell lines resulted in the mainly cytoplasmic accumulation of T286 phosphorylated cyclin D1." (PMID 17407548, 2007). "The suggestion that cytoplasmic sequestration regulates cyclin D1 activity in postmitotic neurons, neonatal cardiomyocytes and cancer cell lines is partly based on experiments that involved subcellular fractionation techniques." (PMID 17407548, 2007). "Cyclin D1 is important for the development and progression of several cancers including those of the breast, oesophagus, bladder and lung." (PMID 17407548, 2007). "Further studies have demonstrated that DIF-3 (30 μM) induces cyclin D1 degradation in cancer cells similarly to DIF-1." (PMID 17407548, 2007). "In many cancers, the impaired ubiquitin-dependent degradation of cyclin D1 is responsible for its elevated levels." (PMID 17407548, 2007). "Our findings provide evidence for the regulation of cyclin D1 activity by cytoplasmic sequestration in several mammalian cancer cell lines and murine tissues." (PMID 16503970, 2006). "Cyclin D1 plays a major role in cell cycle progression and is therefore central to the proliferative ability of many cancers." (PMID 16569247, 2006). "We report that cyclin D1 undergoes increased degradation in the cytoplasm during S phase in a variety of cancer cells." (PMID 17205132, 2006). "Here we show that cyclin D1 is localized predominantly within the cytoplasm of mammalian cancer cells." (PMID 16503970, 2006). "Given the importance of cyclin D1 in human disease, concerted effort has been directed at delineating the mechanisms by which cyclin D1 is dysregulated in cancer." (PMID 16863592, 2006). "We demonstrate that cyclin D1 undergoes increased degradation in the cytoplasm during S phase in a variety of cancer cells." (PMID 17205132, 2006). "We have also demonstrated that ERK/MAPK-mediated cyclin D1 degradation through FBXW8 is required for proliferation of cancer cells." (PMID 17205132, 2006). "Second, cyclin D1 is known to bind and modulate the action of several transcription factors that hold significance in human cancers." (PMID 16863592, 2006). "We have shown by several different experimental approaches, that cyclin D1 is in fact a predominantly cytoplasmic protein in mammalian cancer cell lines." (PMID 16503970, 2006). "Cyclin D1 regulates G1 progression in cancer cells and is overexpressed in various malignant neoplasms." (PMID 17205132, 2006).
cancer (continued). "There are a number of studies that attempted to correlate the level of expression of cyclin D1 and p16 in cancer with prognosis." (PMID 16953893, 2006). "Our work shows that cyclin D1 is destabilized specifically during S phase in cancer cells and that increased degradation is mediated by phosphorylation at Thr286 through the activity of the Ras/Raf/MEK/MAPK signaling cascade." (PMID 17205132, 2006). "To test this idea, we determined by sub-cellular fractionation, the effect of TSA on endogenous cyclin D1 localization in asynchronous human cancer cells." (PMID 16503970, 2006). "It is not clear from our studies that celecoxib directly affects cell cycle distribution by regulating cyclin D1 levels, which is one of the major cyclins known to be upregulated during cancer." (PMID 15987447, 2005). "So far, several studies were done to reveal the prognostic significance of cyclin D1 overexpression in various carcinomas, including CRC." (PMID 15385053, 2004). "In particular, cyclin D1 is a major regulator of proliferation at the level of the cell cycle and is overexpressed in many cancers." (PMID 11953870, 2002). "Our data demonstrate that NDGA selectively inhibits constitutive cyclin D1 expression in both cancer cell lines providing a molecular mechanism of its growth inhibitory properties." (PMID 11953870, 2002). "Overexpression of cyclin D1 has been postulated to play an important role in the development of human cancers." (PMID 10487623, 1999). "Heterogeneous staining of cancer cell nuclei with antibody to cyclin D1 was found in 31.3% of patients (25 out of 80 patients)." (PMID 9459151, 1998). "Cyclin D1 is a cell cycle regulator of G1 progression that has been suggested to play a relevant role in the pathogenesis of several human cancer types." (PMID 9155044, 1997). "Targeting the degradation of cyclin D1 presents a promising approach for cancer therapy." (PMID 41574218, 2026). "However, dysregulation of cyclin D1 is frequently observed in human cancers, with gene amplification and overexpression documented in approximately 50% of breast and esophageal cancers." (PMID 41368202, 2026). "• Exertion of anticancer effects through 3 major pathways: apoptosis (BIRC3, BIRC5, caspase-8, caspase-9, and PARP1), transcriptional dysregulation in cancer (CDKN1A, CDKN1B, MMP9, MYC, JUN, and RELA), and cancer progression (caspase-3, CCND1, CTNNB1, VEGFA, and Wnt-1)." (PMID 39181121, 2025). "Therefore, finding an alternative strategy is imperative to prevent Cyclin D1 activity in cancer and overcome resistance." (PMID 41348684, 2025). "Cyclin D1 is a proto-oncogene protein that is currently the subject of intensive research due to its key role in the cell cycle and the fact that its disruption can lead to cancer development." (PMID 41465498, 2025). "Cyclin D1 is a key modulator of cell cycle dynamics involved in cancer." (PMID 40108111, 2025). "Aberrant overexpression of cyclin D1 is frequently observed in human cancers." (PMID 40408472, 2025). "In several different types of cancer, CCND1 is overexpressed." (PMID 39900661, 2025). "STAT3 is widely recognized as a therapeutic target in multiple cancers and has been shown to transcriptionally regulate key effector proteins such as cyclin D1, vimentin, and survivin, which are critically involved in cell proliferation, migration, and apoptosis." (PMID 41476794, 2025). "Moreover, TZDs facilitate the ubiquitin‐dependent proteasomal degradation of several oncogenic proteins, including cyclin D1 and β‐catenin, further contributing to cancer cell growth inhibition and apoptosis." (PMID 40387523, 2025).
cancer (continued). "Moreover, the inability to degrade cyclin D1 leads to a compromised intra-S-phase checkpoint and elevated cyclin D1 expression, which is frequently observed in several types of malignant tumors and is indicative of a bad prognosis." (PMID 39900661, 2025). "Moreover, it affects cancer-associated fibroblasts by downregulating critical oncogenic markers like MMP-9, MMP-2, c-Myc, and Cyclin D1." (PMID 40722893, 2025). "Similarly, in a study performed in cancer cells, high pH leads to increased expression of Ccnd1, a β-catenin target gene, and increases proliferation rates." (PMID 40526494, 2025). "Cancers often employ a variety of mechanisms to regulate CCND1 expression." (PMID 40233410, 2025). "These compounds inhibit cancer cell proliferation by downregulating cyclin D1 and upregulating caveolin-1, while simultaneously activating both intrinsic and extrinsic apoptotic pathways to induce cell death, including common epithelial carcinomas, myeloma, leukemia, and sarcoma." (PMID 40424719, 2025). "Importantly, the conservation of these molecular mechanisms across cancer types offers an opportunity for the development of cross-cancer therapeutic strategies targeting circFOXK2 and CCND1." (PMID 40233410, 2025). "This heightened dependence on MMEJ may hold significance in cancers with high cyclin D1 expression, notably MCL, presenting a promising target for therapeutic intervention." (PMID 40608419, 2025). "To detect whether GABRD influences cancer cell proliferation and motility abilities via CCND1, we performed a series of rescued functional experiments." (PMID 40145254, 2025). "ETV4, as a canonical transcription factor, could mediate the development and progression in multiple cancers through transcriptionally regulating its targeted genes, such as Cyclin D1, CXCR4, ANXA2 and KDM5D39-42." (PMID 41281746, 2025). "In addition to being an important marker of cancer stemness, β-catenin is found to be a transcription factor for oncogenes represented by Cyclin D1, c-Myc, and PD-L1." (PMID 39949345, 2025). "The overexpression of cyclin D1 in cancer is mediated by CREPT interaction with the C-terminal domain (CTD) of RNAPII, which modulates the phosphorylation status of the CTD and translocates with RNAP II from promoter regions to 3′-untranslated regions (3′UTR) during in vivo transcription." (PMID 40723282, 2025). "In this regard, inflamed visceral adipose tissue becomes a source of TNF-α, which induces pro-angiogenic factor overexpression as well as upregulation of anti-apoptotic factors, such as cyclin D1, cyclin E, and Bcl-2, that contribute to cancer cells’ survival and migration." (PMID 40227577, 2025). "CENPA-YY1-Cyclin D1 (CCND1)/Neurocilin 2 (NRP2) axis can promote cancer." (PMID 40153584, 2025). "On the contrary, pharmacological inhibition of the PI3K/AKT/mTOR pathway may result in the upregulation of Cyclin D1 or other cell cycle regulatory proteins, effectively enabling cancer cells to circumvent the intended therapeutic effects." (PMID 41348684, 2025). "Future studies investigating the precise molecular interactions between circFOXK2 and CCND1, as well as the potential for targeting this axis in clinical settings, could provide avenues for improving treatment outcomes across multiple cancer types." (PMID 40233410, 2025). "Notably, circFOXK2 is also overexpressed in other cancers, including CRC, ESCC, and PRAD, with its expression again closely linked to that of CCND1." (PMID 40233410, 2025). "By enhancing cyclin D1 degradation, it may be possible to sensitize cancer cells to CDK4/6 inhibitors, overcoming resistance and improving therapeutic outcomes." (PMID 40408472, 2025). "The variation in CCND1 expression across these cancers was clearly manifested." (PMID 39188436, 2024).
cancer (continued). "Additionally, CCND1 overexpression is a significant mechanism of therapeutic resistance in various cancers." (PMID 39272991, 2024). "The results showed that compared with the control, ART1-sh cancer cells induced by IL-6 exhibited reduced viability, a lower rate of colony formation, less DNA synthesis, decreased protein levels of gp130, c-Myc, cyclin D1, Bcl-xL, and a reduced p-STAT3/STAT3 ratio (P < 0.05)." (PMID 38504172, 2024). "JUN promotes the expression of cyclin D1, facilitating cancer cell proliferation." (PMID 40259961, 2024). "Similarly, let-7a has also been shown to be downregulated in LC, and its overexpression inhibits cancer cell migration and proliferation by cyclin D1 regulation." (PMID 39766101, 2024). "Cyclin D1, frequently overexpressed in cancers, is regarded as an oncogenic driver." (PMID 38474224, 2024). "Additionally, genetic alteration analysis was performed using the cBioPortal database to examine the prevalence and types of CCND1 alterations across different cancer types." (PMID 39188436, 2024). "In conclusion, CCND1 is a promising biomarker for prognosis and diagnosis in many cancer types." (PMID 39188436, 2024). "The results indicated a consistent negative correlation between methylation levels at these CpG sites: cg03040489, cg04717045, cg04717045, cg03040489, cg05164185, cg12266049, cg09637363, cg26399164, cg00953256, cg18773844 and cg26399164, and CCND1 expression across various cancer types." (PMID 39188436, 2024). "Cyclin D1 works as a controller of cellular growth and has functions for cancer progression." (PMID 38556083, 2024). "miR-449a has been shown to target cyclin D1 and prevent proliferation of cancer cells." (PMID 39173945, 2024). "The CCND1 gene with increased expression in the HG-ESS differed in 13 cancer types." (PMID 38167455, 2024). "Thus, expression levels of c-myc, CD44 and cyclin D1, proteins crucial for cancer cell survival and proliferation, were reduced in A549, H1650, H1975 and H460 non-small-cell lung cancer cells treated with (+)-UA." (PMID 39457512, 2024). "The methylation analysis highlighted hypomethylation of CCND1 across the 13 selected cancer types." (PMID 39188436, 2024). "Cyclin D1 is a well-known protooncogen whose upregulation means more progressive cancer." (PMID 38469406, 2024). "The abnormally high expression of CCND1 in malignant tumors could lead to chromosomal rearrangement and abnormal gene amplification, suggesting that CCND1 may play an important role in tumorigenesis." (PMID 39438468, 2024). "ALA has also been shown to inhibit COX-2 and cyclin D1 expression, which may contribute to its anti-cancer effects." (PMID 39652552, 2024). "Cyclin D1, encoded by the CCND1 gene, is one of the most important regulators in regulating the cell cycle and serves as a significant prognostic and predictive factor across various cancers." (PMID 38256056, 2024). "Many TME-related genes (such as VEGFA, MMP14, CCND1, MAP2K1, SLC2A1) and actin cytoskeleton-associated genes (such as ITGB4, ITGA6, ACTG1, VCL) were downregulated, suggesting a less favorable TME and an altered cytoskeleton network in ISO-treated cancer cells." (PMID 38339062, 2024). "Cyclin D1 regulates the G1-S transition of the cell cycle through phosphorylation of the retinoblastoma (Rb) protein together with CDk4/6 and is often overexpressed or amplified in many types of cancer." (PMID 38238702, 2024). "Existing research has suggested that Cyclin D1 is frequently dysregulated in cancer and could be a vital biomarker for cancer phenotype and disease progression." (PMID 38951593, 2024). "Amplification and/or overexpression of CCND1 is frequently found in a variety of cancers." (PMID 39739897, 2024). "Cyclin D1 is one of the key regulators that performs a central role in the pathogenicity of cancer determining the cell proliferation and overexpressed in cases of cancer, whereas they are properly regulated in normal cells." (PMID 39372197, 2024).
cancer (continued). "Furthermore, downregulation of CCND1 was found by differential methylation analysis in COAD, KIRC, and THCA, indicating a possible involvement of CCND1 methylation in the etiology of these cancers." (PMID 39188436, 2024). "Despite this, no study to date has investigated the role of CCND1 as a diagnostic or prognostic biomarker in cancer." (PMID 39188436, 2024). "Furthermore, iron depletion was reported to suppress human cancer cells growth at G1/S by inducing cyclin D1 proteolysis." (PMID 39255019, 2024). "Disorder of Bcl-3 may upregulate cancer cell proliferation levels by upregulating cyclin D1 and stimulating tumors to undergo G1 phase transition." (PMID 38577985, 2024). "In terms of the cell cycle, Cyclin D1 is an important regulator in the G0/G1 phase, and its expression in normal cells is tightly regulated, but its activity is abnormally enhanced in various ways in some cancers." (PMID 39605083, 2024). "In addition to this, several studies have demonstrated that carotenoids can arrest the cell cycle in the G0/G1 phase through the suppression of cyclin D1 expression, consequently impacting the proliferation of cancer cells." (PMID 38539798, 2024). "Thus, targeting the abnormally activated CDK4/6–cyclin D1 complex has been demonstrated to be a promising therapeutic approach against some cancers." (PMID 39593745, 2024). "This suggests that CCND1 methylation may have a role in regulating the expression of the CCND1 gene in these cancers." (PMID 39188436, 2024). "In addition, it has been reported that F. nucleatum can produce LPS that activates β-catenin signaling, thus enhancing oncogene expression (C-myc and cyclin D1) and promoting cancer cell proliferation." (PMID 39409925, 2024). "Exploring the molecular mechanism of CCND1 isoforms has offer new insight for cancer treatment." (PMID 37024471, 2023). "Therefore, it is a better candidate for anti-cancer drug development, and agents that target cyclin D1 have shown promising potential in cancer treatment." (PMID 36765917, 2023). "Thus, the roles of c-Myc, cyclin D1, and the Wnt pathway in the treatment of cancer have been extensively studied." (PMID 37064948, 2023). "Overexpression of survivin in the nuclei of cancer cells promotes the G1–S cell cycle transition by releasing p21 (known as a cyclin-dependent kinase [Cdk] inhibitor 1) from Cdk4 to activate the cyclin D1/Cdk4 complex, leading to the phosphorylation of the protein retinoblastoma." (PMID 37915752, 2023). "CCND1 ubiquitination by ROC1-CUL1 and FBX4 has been reported to be involved in the progression of cancers but how the CCND1 protein is modulated in HCC is largely unknown." (PMID 36937431, 2023). "We also examined whether cyclin D1 similarly regulated glycolysis in cancer cell lines by measuring lactate production." (PMID 38152849, 2023). "Collectively, these data indicate that MG53 may interfere cancer cell cycle progression via downregulating cyclin D1 protein abundance." (PMID 37414783, 2023). "Moreover, JUP strongly activates c-Myc and cyclin D1 expression and supports cancer progression by mediating survival through the inhibition of apoptosis and promotion of cellular proliferation." (PMID 38203664, 2023). "Furthermore, we highlight the function of CCND1 isoforms in cell cycle, invasion, and metastasis in cancers." (PMID 37024471, 2023). "For example, cancer patients with high cyclin D1 overexpression had poorer median survival." (PMID 37763649, 2023). "Furthermore, inhibition of CCND1 has been found to sensitize cancer cells to chemotherapy and radiation therapy." (PMID 37744271, 2023). "Cyclin D1 together with cyclin-dependent kinase (CDK)-4 are key regulators of the G1 phase of the cell cycle, and they are considered therapeutic targets in BRAF-mutated cancers." (PMID 36674794, 2023). "The mechanism of cyclin D1 activity in cancer appears to be complex." (PMID 36675501, 2023).